TRPA1 (transient receptor potential cation channel subfamily A member 1)
Diseases named in the same sentence as TRPA1 in open-access papers (continued):
Sharing a sentence is not in itself a finding about the gene and the disease.
asthma (continued). "A previous study using ovalbumin (OVA)-induced asthma models demonstrated that TRPA1 activation leads to the release of neuropeptides such as calcitonin gene-related peptide (CGRP), substance P, and neurokinin A, which, in turn, promotes the activation of adaptive immunity and cytokine production." (PMID 41322401, 2025). "Here, we summarize the pathological roles of TRPV1/TRPA1 in asthma." (PMID 40678720, 2025). "However, excessive or chronic TRPA1 activation can contribute to airway hyperreactivity and respiratory conditions such as asthma." (PMID 39022308, 2024). "However, more research is required to identify the involvement of TRPA1 signaling pathway in immune cell function and airway inflammation in asthma." (PMID 39273183, 2024). "In summary, TRPA1 may serve as a promising therapeutic candidate protein among asthma treatment strategies." (PMID 39273183, 2024). "Allergic airway inflammation, often observed in conditions such as allergic rhinitis and asthma, may exhibit a heightened sensitivity to TRPA1 dysfunction." (PMID 39022308, 2024). "TRPA1 is found in sensory neurons, immune cells such as mast cells and T cells, and bronchial epithelial cells, where it plays a significant role in mediating the inflammatory response in respiratory conditions like asthma." (PMID 39664985, 2024). "Consequently, mast cell-mediated effects, notably allergen-induced histamine release, cannot fully elucidate the alleviation of asthma symptoms following TRPA1 antagonism." (PMID 39022308, 2024). "The potential contribution of TRPA1 dysfunction to respiratory diseases such as asthma, Chronic Obstructive Pulmonary Disease, and allergic airway inflammation is a complex interplay between altered sensory perception, inflammatory dysregulation, and structural changes in the airways." (PMID 39022308, 2024). "The expression of TRPA1 has been observed in sensory neurons that innervate the airways, immune cells implicated in the inflammatory response associated with chronic obstructive pulmonary disease (COPD) and asthma." (PMID 37841931, 2023). "Based on the comprehensive review of relevant literature, the author believes that the effect of TRPA1 on asthma is mainly reflected in three aspects: participating in the inflammatory response, mediating the change of cough, and participating in the process of asthma exacerbation." (PMID 37039840, 2023). "TRPA1 is also activated by endogenous factors and promotes inflammation in asthma models." (PMID 37386145, 2023). "Prior work has established mouse models of TDI-induced asthma are TRPA1 dependent." (PMID 36877675, 2023). "In fact, topical menthol treatment is often accompanied by skin irritation, and inhalation of menthol can aggravate asthma in some patients, which may be the role of TRPA1." (PMID 36277488, 2022). "A contribution of TRPA1 to airway inflammation has also been reported in a rat model of asthma." (PMID 35562920, 2022). "TRPA1 has been critically proposed to contribute to airway inflammation in asthma." (PMID 35562920, 2022). "TRPA1 is a non-selective cationic channel, the dysfunction of which is associated with many diseases, such as cough, asthma, ulcerative colitis, pancreatitis, arthritis, diabetic neuropathy, ischemia, multiple sclerosis, stroke, and others." (PMID 35877758, 2022). "However, it does not seem likely that mast cell-mediated effects and especially allergen-induced histamine release by mast cells, can fully explain the alleviation of asthma symptoms after TRPA1 antagonism as observed in vivo." (PMID 33557843, 2021). "Indeed, previous studies from asthma rodent models provide strong support that inhibiting TRPA1 reduces inflammation and bronchoconstriction in response to ovalbumin challenge." (PMID 33953304, 2021). "BI01305834 seems to alleviate asthma symptoms via TRPA1 channels expressed on sensory nerves, however, TRPA1 expressed on other cells types may enhance this protective effect." (PMID 33557843, 2021).
asthma (continued). "As a second aim, we investigated how TRPA1 antagonism could alleviate asthma symptoms in guinea-pig models of allergic asthma." (PMID 33557843, 2021). "Additionally, it has been shown that TRPA1 is an essential factor in the development of asthma/allergic hypersensitivity in mice, while Arg3Cys and Arg58Thr polymorphisms correlate with worse asthma control in children." (PMID 34356881, 2021). "However, many preclinical studies show the potential for TRPA1 antagonism in asthma and other airway disorders, including chronic obstructive pulmonary disease and cough." (PMID 33557843, 2021). "Thus, we provide genetic evidence in a second species for the functional contribution of TRPA1 to airway inflammation in an asthma model." (PMID 31969645, 2020). "Endogenous activators of TRPA1 have also been shown to induce asthma." (PMID 33193423, 2020). "Thus, TRPA1 appears to make a robust, cross-species contribution to airway inflammation in preclinical asthma models." (PMID 31969645, 2020). "Our findings suggest, for the first time, that TRPA1 may play a role in the development of childhood asthma." (PMID 27779810, 2017). "In ALSPAC,TRPA1 associations with asthma were not modified by prenatal paracetamol, although associations with IgE concentration were." (PMID 27779810, 2017). "It is important that our findings are further replicated in adequately powered studies with comparable asthma phenotypes, and we plan to explore interactions between TRPA1 and other oxidant exposures such as tobacco smoke and air pollution on childhood respiratory outcomes." (PMID 27779810, 2017). "Animal data have suggested that the transient receptor potential ankyrin‐1 (TRPA1) ion channel plays a key role in promoting airway inflammation in asthma and may mediate effects of paracetamol on asthma, yet confirmatory human data are lacking." (PMID 27779810, 2017). "It remains to be seen if TRPA1 antagonists attenuate asthma in clinics." (PMID 27827953, 2016). "Another TRPA1 antagonist from Cubist Pharmaceuticals, CB-625 (structure not disclosed), was effective in reducing the late asthmatic response and antigen induced airway hyperresponsiveness upon oral dosing in sheep model of asthma." (PMID 27827953, 2016). "TRPA1 can also be activated chronically in chronic cough, asthma, chronic obstructive pulmonary disease (COPD), and rhinitis, wherein endogenous TRPA1 ligands (e.g., 4HNE, H2O2) and pro-inflammatory mediators (e.g., bradykinin and nerve growth factors) are elevated." (PMID 25640188, 2015). "Paracetamol may also contribute to the increased risk of asthma and COPD, via its reactive metabolite NAPQI through TRPA1-dependent neurogenic inflammatory responses in the airways." (PMID 24718577, 2014). "Interestingly, another TRP channel, TRPA-1, appears relevant to allergen-induced asthma models, since TRPA-1 knockout mice were shown to be more resistant to airway inflammation and hyperactivity than WT mice." (PMID 23631390, 2013). "TRPA1 has been proposed as a sensor of byproducts of oxidative and nitrative stress, and oxidative stress and its by-products, including 4-hydroxy-2-nonenal, have been suggested to contribute to the mechanism of asthma." (PMID 22905134, 2012). "Associations between SNPs in TRPV4 and TRPA1 and cough symptoms in subjects with or without asthma were also not significant after adjusting for multiple testing." (PMID 22443337, 2012). "Most notably, stimulation of TRPA1 excites nociceptive neurons, apparently contributing significantly to physiological pain responses, inflammatory hyperalgesia, neuropathic pain states and irritant responses of asthma." (PMID 21291387, 2011). "Importantly, asthma in many cases is triggered by airborne irritants (such as cigarette smoke components) capable of activating TRPA1 and exciting airway C-fibres." (PMID 21291387, 2011). "TRPA1 has potential as a target for developing new analgesics and agents that treat asthma." (PMID 21291387, 2011).
asthma (continued). "Consequently, antagonism of TRPV1/TRPA1 channels exerts beneficial effects on asthma symptoms." (PMID 40678720, 2025). "Using this model, we have shown that the activation of TRPA1 channels is specifically involved in the exacerbation of innate immunity-mediated eosinophilic airway inflammation under cold air exposure; these findings provide a molecular mechanistic explanation for such asthma exacerbation." (PMID 41322401, 2025). "Therefore, TRPA1 not only has an impact on the pathogenesis of asthma but also may be related to the neurogenic mechanism of bronchitis and COPD in different stages." (PMID 37039840, 2023). "Considering this, targeting TRPA1 could be more effective in non-Th2 asthma." (PMID 37386145, 2023). "Therefore, TRPA1 has attracted attention as a potential asthma drug target." (PMID 37386145, 2023). "Another target of interest is the TRPA1 ion channel, and more specifically, the main receptor of ion channels of the nociceptive system, which can be a critical factor in the development of pain, inflammation (e.g., inflammatory diseases of the respiratory tract, including asthma), and NP." (PMID 35930193, 2022). "In asthma, TRPA1 may be involved in several aspects of the disease." (PMID 33557843, 2021). "This study suggests that TRPA1 may play a role in the development of childhood asthma." (PMID 27779810, 2017). "In addition, a report on transient receptor potential vanilloid 1 (TRPV1) polymorphisms associated with cough in subjects without asthma has been published while recent studies have further shown TRPA1 as a promiscuous receptor for a wide range of stimuli." (PMID 27517941, 2016). "Given their pivotal roles in asthma pathophysiology, TRPV1 and TRPA1 have emerged as promising therapeutic targets for developing novel disease-modifying agents." (PMID 40678720, 2025). "Recently, the role of TRPV1/TRPA1 activation in exacerbating asthma symptoms and its specific mechanisms have become increasingly clear, sparking interest among asthma drug development researchers in targeting TRPV1/TRPA1 antagonists." (PMID 40678720, 2025). "During the course of asthma, TRPV1/TRPA1-mediated calcium influx induces the release of neuropeptides, including SP, NKA, NKB, and CGRP." (PMID 40678720, 2025). "While some studies confirm that certain CHM metabolites can alleviate asthma symptoms by activating TRPV1/TRPA1, drug development has primarily focused on TRPV1/TRPA1 inhibitors." (PMID 40678720, 2025). "In asthma models induced by tobacco extract and PM2.5, inhibiting TRPA1 can reduce the expression of IL-1β and IL-18." (PMID 39735214, 2024). "Among TRP channels, TRPA1, TRPV1, and TRPV4 are relevant to asthma due to their widespread expression in the respiratory system." (PMID 39664985, 2024). "Herein we demonstrate that, like asthma models, TDI-induced dermatitis models are partially TRPA1 dependent." (PMID 36877675, 2023). "The expression of TRPA1 is increased in lung tissues and CD4+ T cells in an OVA-induced mouse model of asthma, accompanied with the development and exacerbation of asthma." (PMID 35784284, 2022). "Similar findings were reported in a mouse model of chemical induced asthma, where AITC was unable to induce AHR in toluene-2,4-diisocyanate-sensitized mice while TRPA1 blockage or knock-out prevented the development of AHR." (PMID 33557843, 2021). "The TRPA1 antagonists CB-189625 and GRC17356 are undergoing phase I clinical trials for the fight against chronic cough in asthma patients." (PMID 34356881, 2021). "In the current study, we evaluated the efficacy of the novel TRPA1 antagonist BI01305834 against AHR and inflammation in guinea-pig models of asthma." (PMID 33557843, 2021). "In particular, TRP channels showing high levels of expression in sensory neurons such as TRPV1, TRPA1, and TRPM8, have been considered as targets for indications where sensory neurons play a fundamental role, such as pain, itch, and asthma." (PMID 31969645, 2020).
asthma (continued). "Extended and prolonged inflammation can lead to cough, asthma, and chronic obstructive pulmonary disease (COPD) and, interestingly, TRPA1 expression has been demonstrated in immune cells involved in the inflammatory response in asthma and COPD." (PMID 31197115, 2019). "Various noxious chemicals and environmental/industrial irritants that activate TRPA1 happen to be triggers for asthma or reactive airways dysfunction syndrome (RADS) and are known to worsen asthma attacks." (PMID 27827953, 2016). "This review synthesizes recent mechanistic insights into how dysregulated calcium signaling-via transient receptor potential (TRP) channels (e.g., TRPV1, TRPA1), store-operated calcium entry (SOCE), L-type calcium channels (LTCCs), and mechanosensitive Piezo1-drives key asthma phenotypes." (PMID 41437399, 2025). "Therefore, we conclude in this study the TRPA1 is the primary mediator of TSLP induction in response to cold exposure, potentially contributing to asthma exacerbations." (PMID 41322401, 2025). "Several TRP channels, including TRPA1, are being explored as pharmacological targets for asthma; however, what type of asthma TRPA1 is specifically involved in has remained unclear, and no drug targeting TRPA1 channels has been clinically developed." (PMID 41322401, 2025). "Additionally, certain air pollutants, such as dust and nitrogen compounds, can activate TRPA1 and TRPV1, promoting and worsening existing asthma." (PMID 38365763, 2024). "TRPA1 has been found to contribute to E-cadherin and β-catenin dysfunction in TDI-induced asthma." (PMID 34356881, 2021). "The activation of TRPA1 by DEP is also responsible for cardiac dysfunction, respiratory responses (by increased release of glutamate triggered by the acrolein component), reduced asthma control and locomotor hyperactivity." (PMID 33803491, 2021). "In this study, we evaluated the efficacy of the novel TRPA1 antagonist BI01305834, and investigated how this antagonist could alleviate asthma symptoms in guinea-pig models of allergic asthma, via neuronal and non-neuronal pathways." (PMID 33557843, 2021). "Therefore, TRPA1, TRPV1, and TRPV4 are most promising pharmacological targets for new asthma therapeutics and already effective modulators are ready for use in clinical trials." (PMID 30717260, 2019). "Experiments with TRPA1 KO mice revealed reduced airway infiltration by inflammatory leukocytes accompanied by decreased production of pro-inflammatory cytokines and neuropeptide release in the airways in the ovalbumin (OVA) asthma model." (PMID 27827953, 2016). "If neurogenic inflammation plays a role in murine models of asthma but no role in human asthma, this does not exclude a TRPA1 contribution to the disease via non-neuronal mechanisms." (PMID 22905134, 2012). "Therefore, how do some CHM metabolites provide therapeutic effects for asthma through TRPV1/TRPA1 activation without inducing asthma symptoms?" (PMID 40678720, 2025). "These experimental observations suggest that the activation of TRPV1 and TRPA1 might attenuate Th2 responses and inhibit the progression of airway inflammation, indicating that TRPV1 and TRPA1 may have dual roles in the pathogenesis of asthma." (PMID 40678720, 2025). "Overall, TRP channels, including TRPA1, TRPV1, and TRPV4, contribute to asthma pathophysiology and the immune response by regulating inflammatory processes, immune cell recruitment, and airway remodeling, making them potential therapeutic targets for asthma management." (PMID 39664985, 2024). "Therefore, based on these studies, it is suggested that reduced activation of TRP family channels, especially TRPA1, TRPV1 and TRPV4, may be potential targets for new therapies for asthma." (PMID 37841931, 2023). "The role of TRPA1 in the activation of sensory nerves of the lungs and the development of bronchoconstriction has been established for both allergic and non-allergic asthma." (PMID 34356881, 2021).
asthma (continued). "Inhibition of TRPA1 alone or TRPA1 and TRPV1 simultaneously shows better effects than the inhibition of TRPV1 alone, suggesting that TRPA1 is more sensitive to the oxidative stress induced by PM2.5 than TRPV1, and that TRPA1 might have a more important role in asthma generation." (PMID 33803491, 2021). "In summary, this indicates that the protective effect of BI01305834 on allergen-induced changes in asthma models was probably not mediated via TRPA1 channels on mast cells, as both in vivo and ex vivo these effects were observed at lower concentrations already." (PMID 33557843, 2021). "This review will focus on TRP channels (TRPA1, TRPC6, TRPV1, and TRPV4), predominantly expressed in non-neuronal lung tissues and their involvement in pathways associated with diseases like asthma, cystic fibrosis, chronic obstructive pulmonary disease (COPD), lung fibrosis, and edema formation." (PMID 30717260, 2019). "However the limited clinical evidence for the role of neurogenic inflammation in asthma or chronic obstructive pulmonary disease raises an alternative possibility that airway inflammation is promoted by non-neuronal TRPA1." (PMID 22905134, 2012). "Here we present evidence that non-neuronal cells in human and murine airways express TRPA1, where it promotes a non-neurogenic inflammatory response, which may contribute to asthma and COPD." (PMID 22905134, 2012). "However, evidence implicating TRPA1 in asthma in humans is lacking." (PMID 27779810, 2017). "Across neuronal and non-neuronal tissues expressing TRPA1, this increased sensitivity and inward ion conduction could account for the hyperexcitability-hypersensitivity observed in CRAMPT syndrome patients (e.g., cold hyperalgesia, parasthesis, itch, asthma, and GI reflux)." (PMID 37208332, 2023).